DRC11L (dynein regulatory complex subunit 11 like)
Synonyms: IQCA1L; IQCA1P1; TCAG_9762
Tractability: No criterion of Open Targets' tractability assessment is met for any kind of drug.
Gene: Protein-coding gene on chromosome 7 (151,190,873 to 151,205,496, reverse strand). Ensembl gene ENSG00000278685.
Gene Ontology:
Molecular function: ATP hydrolysis activity; microtubule severing ATPase activity; ATP binding
Biological process: microtubule severing
Homologues: Orthologues: chimpanzee IQCA1L (97% identical), macaque IQCA1L (94% identical), dog IQCA1L (79% identical), pig IQCA1L (77% identical), mouse Iqca1l (76% identical), rat Iqca1l (75% identical), guinea pig IQCA1L (72% identical), rabbit IQCA1L (63% identical), Drosophila melanogaster CG16789 (39% identical), Drosophila melanogaster CG14183 (27% identical). Paralogues in human: DRC11 (47% identical).